ATM (ATM serine/threonine kinase)
Diseases named in the same sentence as ATM in open-access papers (continued):
Sharing a sentence is not in itself a finding about the gene and the disease.
tumor (continued). "NGS and IHC analyses of the tumor revealed multiple defects in DDR genes and proteins, specifically, heterozygous truncating mutations in CHK1, FANCM, RAD50, POLD1, and FANCP; compound heterozygous truncating mutations in ARID1A; and loss of ATM and ARID1A protein by IHC." (PMID 32568634, 2020). "However, detection of ATM alterations alone might be insufficient to identify these sensitive tumours." (PMID 31806540, 2020). "However, the mutation spectrum is broad and the impact on ATM functionality, tumour behaviour and response to therapy is not fully established." (PMID 32444694, 2020). "Moreover, in the loss of ATM or ATR functions, genome instability such as mutation or deletion will promote cell survival, potentially resulting in cancerous formations and ultimately tumor promotion." (PMID 31772936, 2019). "The results showed that expressions of ATM were increased in tumor issues of A549cisR cell-derived xenografts compared to tissues of A549P cell-derived xenografts, consisting with the in vitro result showing increased ATM expression level in cisplatin-resistant cells compared to the parental cells." (PMID 30961670, 2019). "If a consensus was made to define ATM as a gene with clinical utility, specific pathological and genomic features associated with ATM inactivation in tumours could help identify subjects with no strong personal or family history of BC." (PMID 29665859, 2018). "Moreover, suppression of ATM may significantly contribute to the activation of mTORC1 observed in hypoxic tumors and can promote tumor cell survival through autophagy regulation." (PMID 29616191, 2018). "Immunohistochemistry analysis for MSH6 in the tumor of patient HPC332 showed normal MSH6 expression, thus reducing the likelihood that the MSH6 c.1729C>T variant is a PrCa risk factor and rendering the ATM mutation c.8560C>T the most likely risk variant in this patient." (PMID 29659569, 2018). "Low to moderate lymphocytic infiltration was observed in ATM-associated tumours (data not shown), but this information was not available in the PICBIM, so no comparison could be performed." (PMID 29665859, 2018). "This ATM expression index was calculated by dividing average ATM pixel intensity within the pan-cytokeratin-positive malignant cell area by the average ATM pixel intensity within the corresponding vimentin-positive and pan-cytokeratin-negative tumour-associated stromal area." (PMID 28418844, 2017). "Increased tumour growth inhibition has been reported when this has been combined with carboplatin or radiotherapy in vivo, and single-agent anti-tumour activity has been seen in ATM-deficient but not ATM-proficient xenograft models." (PMID 29069866, 2017). "Thus, within the context of DNA repair ATM functions as a tumor suppressor (classical function)." (PMID 29348882, 2017). "Our model identified mutations in VHL (von Hippel-Lindau), PBMR1, BAP1, MTOR, ATM, SETD2, KDM5C and PTEN (phosphatase and tensin homolog), as well as copy number changes in MLH1, DUSP1 and RANDBP17 as significantly associated with various TF activity changes across tumours." (PMID 28139702, 2017). "We expect that somatic changes in ATM would lead to a loss of ATM expression that could be detected by quantifying the relative expression of ATM protein within the malignant versus the stromal component of the tumour - a concept introduced here as the ATM expression index (ATM-EI)." (PMID 28418844, 2017).
tumor (continued). "“in situ MCL” is very low risk for the development of classic MCL, however, the acquired alterations in the DNA damage response pathway, such as ataxia-telangiectasia mutated (ATM), or cell cycle checkpoint kinase 2 (CHK2) inactivating mutations may facilitate the development of the tumor." (PMID 29246179, 2017). "Thus, we hypothesized that tumor cells induce ATM protein expression in order to maintain its activity as a consequence of the prolonged damage induced in combination setting and the inability to repair it." (PMID 29212503, 2017). "Importantly, we find that these results are translatable to therapeutic ATM inhibition in human patient-derived GBM stem cells, and that combining ATM inhibition with PDGFRA inhibition results in synergistic tumor cell killing with minimal effects on untransformed cells." (PMID 26984279, 2016). "Thus, in contrast to normal cells, phospho-ATM may accumulate in tumor cells after CDV exposure because of persistent DNA damage." (PMID 27331622, 2016). "In this study, ATM low associated poorer survival outcomes and this effect was more pronounced in the hormone negative breast cancers where a multivariate analysis demonstrated that ATM low predicted survival independent of tumor size and lymph node status." (PMID 27259260, 2016). "Furthermore, the autophagy suppressing functions of Ataxia-telangiectasia mutated (ATM) kinase inhibitors and plant-derived compounds, such as resveratrol, have been demonstrated, including the reduction of tumor volumes and the prolonged survival in mouse xenograft." (PMID 26830677, 2016). "In addition, ATM-low tumours showed significantly more lymph node metastasis." (PMID 26220524, 2015). "However, ATM can also exert pro-angiogenic and tumor-promoting effects." (PMID 26000250, 2015). "While the classic tumor suppressor properties of ATM are related to a requirement for the protein for normal DNA repair, our results provide evidence that the antiproliferative consequences of ATM inhibition arise as a consequence of the novel role for ATM in mitochondrial function." (PMID 23185347, 2012). "An interesting question is whether low ATM expression may correlate to other tumor characteristics." (PMID 22420423, 2012). "In addition to a role in tumor suppression, ATM also has a role in motor function." (PMID 21980358, 2011). "Therefore, further investigation on the association between ATM and NFκB in GBM might expand the targeted therapeutic options to avoid NFκB-dependent tumor cell survival and thus resistance to chemotherapeutic drugs." (PMID 21896960, 2011). "Therefore, identification of the molecular linkage between the kinase ATM and NF-κB signaling in tumor response to therapeutic IR will lead to a better understanding of cellular response to IR, and will promise novel molecular targets for therapy-associated tumor resistance." (PMID 22096476, 2011). "Thus, inhibition of FANCD2 monoubiquitylation (FANCD2-Ub), a key step in the FA pathway, might target tumor cells defective in ATM through synthetic lethal interaction." (PMID 20043851, 2009). "We report that MMR-deficient cells retain sensitivity to brostallicin, thereby extending the list of potential anticancer agents for use in the treatment of MMR-deficient tumours, and that brostallicin-induced cytotoxicity may not require ATM and DNA-PK." (PMID 14562032, 2003). "To increase clinical relevance we analyzed published results of clinical trials and reported blood tumor barrier (BTB) penetration of the WEE1 inhibitor adavosertib and the ATM/ATR inhibitor BAY-1895344." (PMID 41585496, 2026). "ATM inhibition impairs the cellular DSB repair via homologous recombination, leading tumor cells to depend on remaining functional compensatory DDR pathways, such as ATR." (PMID 40875525, 2025).
tumor (continued). "Inhibiting the activity of ATM protein can effectively reverse the EMT process, thus alleviating tumor progression." (PMID 40075162, 2025). "The three key DNA repair pathways ATM, ATR, and DNA-PK act as core monitors of DNA damage response, significantly influencing tumour development and treatment outcomes." (PMID 40256842, 2025). "Supporting these observations, we found that several kinases involved in DNA damage response, ATM, ATR, and PKCA, showed upregulated kinase activity in sensitized tumor cells following both T cell and TNF treatment." (PMID 41315176, 2025). "The findings largely validated previous reports highlighting the importance of tumor suppressor genes such as ATM, BRCA1, BRCA2, and PALB2 for a limited number of tumor types." (PMID 40072281, 2025). "Key predictors included clinical variables (age, tumor size, NPI, radiotherapy) and molecular markers (ATM, HERC2, AKT2, FOXO3, CYP3A43)." (PMID 41300329, 2025). "Feature selection was performed using the Boruta algorithm, which revealed that both clinical parameters (e.g., age, tumor size, NPI, radiotherapy) and transcriptomic biomarkers (e.g., ATM, HERC2, AKT2, CYP3A43, FOXO3) provided strong prognostic contributions." (PMID 41300329, 2025). "In addition to the tumor suppressive character of ATM/Chk2 signaling, recently, CCNDBP1 (cyclin D1 binding protein 1), a protein associated to chemotherapy-induced damage rescuing, has been found as a possible linker between the ATM/Chk2 signaling and chemoresistance." (PMID 40422251, 2025). "ATM/ATR inhibitors specifically target key kinases in the DDR pathway, thereby interfering with the cell cycle checkpoint regulatory network in tumor cells." (PMID 41473689, 2025). "Inhibiting the ATM/Chk2 and ATR/Chk1 axes can sensitize tumor cells to DNA-damaging agents, particularly in tumors with DDR deficiencies." (PMID 40422251, 2025). "In this study, the inverse correlation between ATM and CD8+ T cells and tumor-infiltrating lymphocytes (TILs) was confirmed by immunochemical staining of 191 TNBC specimens." (PMID 40825766, 2025). "In this study, we performed single-cell sequencing and immunohistochemical (IHC) analysis of tumor tissues from TNBC patients and found that the expression of ATM was significantly negatively correlated with the expression of TILs, MHC-I and CD8+ T cells." (PMID 40825766, 2025). "Among them, cell cycle inhibitors, including Smads and CDKNs, were down-regulated while CDKs, CCNs, E2Fs ATM, ATR, ERCC6, MCMs, and BRCA1 were up-regulated, consistent with a tumor-promoting effect." (PMID 39759123, 2025). "PLX038, a PEGylated SN-38 formulation designed to improve pharmacokinetics and tumor targeting, enhances therapeutic efficacy in HRD, ATM- or BRCA-mutant tumors." (PMID 41190241, 2025). "What’s more, DNA damage can enhance the expression of PD-L1, facilitating tumor evasion and hindering the recruitment of CD8 T cells, partly by activating ATM/ATR/CHK1 pathway through IRF1 signaling." (PMID 40740769, 2025). "For genes that promote DNA damage repair (e.g., ATM/ERCC1), DNA methylation can increase the sensitivity of tumors to radiation, while demethylation leads to radiotherapy resistance in tumor cells." (PMID 40675967, 2025).
tumor (continued). "Specifically, PIWIL4, SATB1, GSE1, NCOR1, SAP30L, ATM, and BMI1 were significantly downregulated in tumor tissues relative to normal controls, while BUB1, CHEK1, MASTL, DNAJC2, UBE2D1, and SSRP1 showed pronounced upregulation." (PMID 41208974, 2025). "Upregulation of NK cell activating NKG2D ligands by DNA damage sensing proteins ATM and ATR, lead to NK cell activation against tumor cells." (PMID 38253555, 2024). "In melanoma cancer cells, the MAGE protein upregulates ATM-dependent pS824-TRIM28 by promoting the binding of TRIM28 to ATM, thereby enhancing DDR and promoting tumor progression." (PMID 39100077, 2024). "Thirdly, LINC-PINT exerts regulatory control over specific pathways, such as the ATM/ATR-Chk1/Chk2 pathway, significantly influencing tumor cell DNA repair mechanisms." (PMID 38553526, 2024). "Previous study demonstrated that the knockout of caspases, nucleases and ATM significantly deceases the phosphorylation of STAT3, the expression of stem cell marker, and reduces the ability of tumor spheres formation." (PMID 38977663, 2024). "The inter-group expression difference analyses for tumor genes implied that APC, ATM, BARD1, BRAF, and BRCA1 gene expression varied among patients in these two groups." (PMID 38338834, 2024). "In line with this, it has been shown that radiotherapy can activate ATM, leading to the inhibition of SLC7A11, reduced cysteine uptake, ferroptosis activation, and tumor growth retardation." (PMID 38778030, 2024). "Together, our data reveal that SIRT2 acts as a tumor suppressor by promoting OGG1 transcription and increasing BER efficiency in an ATM/ATR-dependent manner." (PMID 38554113, 2024). "GZ17-6.02 interacted with bortezomib to enhance autophagosome formation and autophagic flux, and knock down of ATM, AMPKα, ULK1, Beclin1 or ATG5 significantly reduced both autophagy and tumor cell killing." (PMID 38441437, 2024). "Tumours were allowed to form, and mice (n = 5–7) bearing tumours of ~220 mm3 were treated for 28 days with the EZH2 inhibitor, GSK126, and the ATM inhibitor, AZD1390, or the combination of both drugs." (PMID 38519707, 2024). "When a single low dose of MS ~ SN-38 was administered IT to 22Rv1 ATM–/– xenografts and oral TLZ was administered QD, high anti-tumor synergy of the combination was observed." (PMID 38890412, 2024). "Major tumor suppressors are among genes that we detected to be hypermethylated and silenced in PTCL, e.g., ATM, which plays a critical role in DNA repair and whose functions are often compromised in PTCL through acquired genetic alterations." (PMID 39189258, 2024). "Despite the limited mechanistic evidence, there are reports that targeting CDD repair (such as through inhibitors against ATM, PARP and potentially HDACs) can exacerbate the effects of high-LET radiation in promoting tumour cell killing." (PMID 36902352, 2023). "Radiotherapy-activated ATM and IFNγ-induced STAT1 signalling jointly repress SLC7A11 to reduce cystine uptake and enhance tumor lipid peroxidation and ferroptosis." (PMID 37714846, 2023).
tumor (continued). "In contrast, the prevention of tumor-specific T-cell senescence via ATM and/or MAPK signaling inhibition combined with anti-PD-L1 checkpoint blockade can synergistically enhance anti-tumor immunity and immunotherapy in vivo." (PMID 38136380, 2023). "Faulhaber EM showed that DNA-PK, ATM, and ATR kinase inhibitors combined with ionizing radiation can increase HNSC tumor cell death while preserving normal tissue cells." (PMID 36941602, 2023). "Finally, to address whether the introduction of NLRP3 into NLRP3-deficient NSCLC tumor cell lines would improve ATM activation, we re-expressed NLRP3 using a doxycycline-inducible system in A549 and H292 cells, and evaluated ATM activation after IR by assessing the number of P-ATM and γH2AX foci." (PMID 36746533, 2023). "Furthermore, in the clinic, it remains unclear whether patients with tumours harbouring ATM alterations would benefit from DDR inhibitor treatments, particularly as monotherapy, and importantly, there is no generally accepted best strategy to define ATM deficiency for patient selection." (PMID 37627223, 2023). "ATM inhibitors radiosensitized NSCLC by inhibiting IR-induced EGFR activation and can be used in EGFR-resistant tumor cells for radiotherapy." (PMID 36865554, 2023). "In preclinical studies, the classical components of cell-cycle progression and DNA-damage repair, such as ATM, DNA-PKcs, ATR, CHK1, CHK2 and WEE1, have shown to be very promising targets for radiosensitizing tumor cells by applying small-molecule inhibitors." (PMID 36313934, 2023). "The inhibition of ATM expression, which prevents ATM from inducing the activation of ATM-CHK2 and ATR-CHK1 signaling cascades, improves the sensitivity of tumor cells to RT." (PMID 37322433, 2023). "On the other hand, inhibition of ATM has been shown to reduce cell migration, while concomitant administration of AZD0156 (ATM inhibitor) and radiotherapy appears to reduce tumor growth and migration rate in both HPV(+) and HPV(−) HNSCC cell lines." (PMID 36769087, 2023). "Co-inhibition of WEE1 and ATM can reduce the expression of cytokines such as MMP-9 and IL-8, which are closely related to the migration and invasion abilities of tumor cells." (PMID 37305685, 2023). "Our research discovered that HIF1A and ATM are crucial genes in the process of CIH that leads to ferroptosis and that changes in the immunological microenvironment promote the progression of tumor disorders such as THCA." (PMID 36937508, 2023). "Increased p-TBK1 levels was also found in various murine tumor cells including B16-F10, MC-38 and CT26 and LLC in response to ATM inhibition." (PMID 36778120, 2023). "A review of the tumor CGP results revealed that two of these VUS alterations, one in ATM and one in BRIP1, were identified, but classified as benign and filtered from the final report." (PMID 35962742, 2023). "The limitations of this study were the low number of evaluable ATM PDX models and, subsequently, the inability to assess potential tumour type differences." (PMID 37627223, 2023).